TMCO5B (transmembrane and coiled-coil domains 5B (pseudogene))
Synonyms: TMCO5BP
Gene: Transcribed unitary pseudogene on chromosome 15 (33,235,750 to 33,246,603, reverse strand). Ensembl gene ENSG00000215296.
Subcellular location: Membrane